PCDHGA1 (protocadherin gamma subfamily A, 1)
Description:
Potential calcium-dependent cell-adhesion protein. May be involved in the establishment and maintenance of specific neuronal connections in the brain.
Synonyms: PCDH-gamma-A1
Tractability: Antibody: UniProt places it where antibodies can reach, with medium confidence; UniProt predicts a signal peptide or a membrane-spanning region; its Gene Ontology location is reachable by antibodies, with medium confidence.
Gene: Protein-coding gene on chromosome 5 (141,330,514 to 141,512,975, forward strand). Ensembl gene ENSG00000204956.
Subcellular location: Cell membrane
Subcellular location (Human Protein Atlas): Plasma membrane; Vesicles; Cytosol; Nucleoplasm
Gene Ontology:
Molecular function: cell adhesion molecule binding; calcium ion binding
Biological process: cell adhesion; homophilic cell-cell adhesion
Cellular component: plasma membrane; membrane
Genetic constraint (gnomAD): Loss-of-function variants: 32 observed, 60.7 expected, observed/expected ratio (o/e) 0.53, 90% interval 0.4 to 0.71. The upper end of that interval is the gene's LOEUF score, 0.71, which puts it in group 2 of 6, group 1 being the genes least tolerant of losing a copy. Missense variants: 1,205 observed, 1,250.2 expected, observed/expected ratio (o/e) 0.96, 90% interval 0.92 to 1.01. Synonymous variants: 498 observed, 529.12 expected, observed/expected ratio (o/e) 0.94, 90% interval 0.87 to 1.01.
Homologues: Orthologues: mouse Pcdhga1 (83% identical), chimpanzee PCDHGA1 (82% identical), guinea pig PCDHGA1 (72% identical). Paralogues in human: PCDHGA2 (76% identical), PCDHGA3 (75% identical), PCDHGA6 (75% identical), PCDHGA10 (75% identical), PCDHGA5 (75% identical), PCDHGA7 (74% identical), PCDHGA12 (74% identical), PCDHGA4 (74% identical), PCDHGA8 (74% identical), PCDHGA11 (73% identical), PCDHGA9 (72% identical), PCDHGB5 (52% identical), and 49 more.
Diseases named in the same sentence as PCDHGA1 in open-access papers:
PCDHGA1 is named in the same sentence as 13 diseases in open-access papers, as found by Europe PMC text mining. Sharing a sentence is not in itself a finding about the gene and the disease. The quoted sentences say what the papers report.
allergic reactions (1 paper, 2025). "Alterations in the expression or methylation of PCDHGA1 could influence immune responses and contribute to the development or resolution of allergic reactions." (PMID 41394805, 2025).
atherosclerosis (1 paper, 2021). A disease characterized by the build-up of fatty material and calcium deposition in the arterial wall resulting in partial or complete occlusion of the arterial lumen. "In addition, a SNP in PCDHGA1 is associated with carotid artery–intima media thickness (IMT) in humans as readout of atherosclerosis, and DIO3 is enhanced in cardiac tissue in heart failure and ventricular remodeling." (PMID 34895303, 2021).
colorectal cancer (1 paper, 2022). A primary or metastatic malignant neoplasm that affects the colon or rectum. "A functional role for the hypermethylation and gene silencing of PCDHαβγ family genes (PCDHAC2, PCDHB7, PCDHB15, PCDHGA1 and PCDHGA6) was also identified recently in colorectal cancer influencing the WNT/B-catenin pathway implicated in proliferation, survival and migration." (PMID 36443814, 2022).
diffuse astrocytoma (1 paper, 2025). A low-grade (WHO grade II) astrocytic neoplasm. "“MYB- or MYBL1-altered diffuse astrocytoma” is a rare entity defined by a canonical fusion event of MYB- or MYB1L, with the most common partner genes PCDHGA1, MMP16, and MAML2." (PMID 40392954, 2025).
glioma (1 paper, 2022). A benign or malignant brain and spinal cord tumor that arises from glial cells (astrocytes, oligodendrocytes, ependymal cells). "We found MYB- translocations with exon 2 or 3 of PCDHGA1 5/10 and 4/10 grade II gliomas respectively, and MYBL1 rearrangements in 6/9 of the samples examined." (PMID 35574540, 2022).
cardiovascular diseases (1 paper, 2021). "Seven of these DMPs (25%) could be allocated to a gene that was previously associated with cardiovascular diseases (HDAC4, IGF2BP3, CASZ1, SDK1, PCDHGA1, DIO3, PTPRN2)." (PMID 34895303, 2021).
PCDHGA1 also shares sentences with these, for which no sentence is quoted: heart failure (1 paper); oligodendroglioma (1); pilomyxoid astrocytoma (1); pleomorphic xanthoastrocytoma (1); septal defects (1); Sotos syndrome (1); T cell lymphomas (1).